WT1 (WT1 transcription factor)
Diseases named in the same sentence as WT1 in open-access papers (continued):
Sharing a sentence is not in itself a finding about the gene and the disease.
ovarian carcinoma (97 papers, 2006 to 2026). A malignant neoplasm originating from the surface ovarian epithelium. "Although initially described as a tumor suppressor gene, WT1 has been shown to demonstrate oncogenic behavior in several malignancies, particularly ovarian cancer, and is strongly associated with serous ovarian carcinoma." (PMID 41930078, 2026). "In conclusion, we have identified important signaling pathways involving WT1 that affect ovarian cancer, and distinguished three differentially expressed genes regulated by WT1 associated with the prognosis of ovarian cancer." (PMID 34692659, 2021). "Our research has identified related genes and signaling pathways in ovarian cancer that are affected by WT1, and identified genes that are associated with WT1 and affect the prognosis of ovarian cancer." (PMID 34692659, 2021). "We evaluated the expression of mucin-1 (MUC1), cytokeratin 8/18 (CK 8/18) and Wilms’ tumor 1(WT-1), all diagnostic markers of ovarian cancer, and vimentin and CD44 were also analyzed." (PMID 32392708, 2020). "In ovarian cancer, WT1 expression is related to tumor type, grade, and stage, with WT1 expression highly associated with poor overall survival." (PMID 33167428, 2020). "Other frequently used markers include WT1 and CA 125, which are associated with primary ovarian carcinoma." (PMID 28730323, 2017). "Incorporation of WT1 immunohistochemistry into routine diagnostic practice may enhance tumor classification and provide insights into disease progression in ovarian cancer." (PMID 41930078, 2026). "Furthermore, WT1 also exhibits oncogenic activity, and its overexpression has been well demonstrated in ovarian cancer; thus, WT1 immunohistochemical detection is considered as a diagnostic marker of ovarian cancer." (PMID 40963863, 2025). "Similarly, gdRFU 3459, protective for ovarian cancer, harbored WT1-specific TCR47, a marker recognized for its diagnostic and prognostic significance." (PMID 39428403, 2024). "Our study has identified potential therapeutic targets and signaling pathways associated with WT1 expression, which may lead to the development of targeted drugs for the treatment of ovarian cancer to increase the efficacy of combination treatment." (PMID 34692659, 2021). "Wilms’ tumour 1 (WT1) is a tumour-associated antigen expressed in many ovarian cancers." (PMID 30057405, 2018). "To assess whether loss of WT1 results in inhibition of ovarian cancer cell colony formation, we performed a soft-agar assay." (PMID 28288142, 2017). "Therefore, impairment of WT1-transcriptional activity may pose a risk factor for the development of testicular and ovarian cancer through the dysregulation of DAX1 and SF1 proteins." (PMID 35610319, 2022). "The research indicated that the presence of WT1 and CA-125 immunoreactivity in ovarian cancer suggests the probability of it being a primary tumor." (PMID 40385462, 2025). "Surprisingly, within TCGA, tWT1 isoforms were exclusively identified in ovarian cancer (TCGA-OV), which is also the subset with the highest WT1 expression." (PMID 38977895, 2024). "Lung adenocarcinoma-related markers were evaluated including Thyroid transcription factor-1 (TTF-1) and Napsin A, and ovarian cancer-related markers including pair box gene 8 (Pax-8) and Wilm’s tumor gene 1(WT-1)." (PMID 37337182, 2023).
ovarian carcinoma (continued). "To overcome this limitation, we describe an engineered cell with both dual targeting and orthogonal cytotoxic modalities directed against two tumor antigens that are highly expressed on ovarian cancer cells: cell surface Muc16 and intracellular WT1." (PMID 37214945, 2023). "Breast and ovarian carcinomas have ER nuclear positivity, whereas WT-1 nuclear expression in tumor cells favors ovarian carcinoma." (PMID 36938247, 2023). "In ovarian cancer, therapeutic vaccines targeting tumor-associated antigens, such as NY-ESO-1 and WT1, have been the subject of investigation in clinical trials." (PMID 38075052, 2023). "Wilms’ Tumor 1 (WT1), which is overexpressed in ovarian cancer cells, is a promising target for tumor-directed immunotherapy for ovarian cancer due to its prevalence and specificity." (PMID 36900251, 2023). "The aim of our open-label, non-randomized phase I study was to assess the safety of a WT1 peptide vaccine (galinpepimut-S) in combination with nivolumab in patients with WT1-expressing ovarian cancer in second or third remission." (PMID 36900251, 2023). "In cultured ovarian cancer cells and xenograft mouse models, WT1 depletion significantly reversed EMT, inhibited cell migration and invasion, and prevented metastasis of cancer cells." (PMID 35465313, 2022). "Our study results indicated that among pan-cancer samples, WT1 showed the highest expression in ovarian cancer." (PMID 34692659, 2021). "In general, our systematic analysis will further elucidate the specific role played by WT1 in the pathogenesis of WT1 of ovarian cancer at the molecular level." (PMID 34692659, 2021). "The analysis results showed that compared with other cancers, WT1 was highly expressed in ovarian cancer." (PMID 34692659, 2021). "We used transcriptome technology and bioinformatics analysis to study the specific mechanisms induced by WT1 in regulating the process of ovarian cancer." (PMID 34692659, 2021). "Enhanced expression of WT-1 has been reported in colorectal, breast, and epithelial ovarian cancers." (PMID 34314463, 2021). "The WT2725 dosing emulsion was administered as a monotherapy to patients with advanced malignancies (glioblastoma, AML, NSCLC, and ovarian cancer) known to overexpress the WT1 protein in the majority of patients." (PMID 34785698, 2021). "Transwell assay was used to further verify the effect of WT1 upregulation on ovarian cancer cell line SKOV3." (PMID 34692659, 2021). "CCK and transwell assay were used to verify the effect of WT1 downregulation on the proliferation, migration and invasion of ovarian cancer cell line SKOV3." (PMID 34692659, 2021). "In this study, following WT1 gene interference in the ovarian cancer cell line SKOV3, the DEGs were mainly enriched in the FoxO, AMPK, and Hippo signaling pathways." (PMID 34692659, 2021). "At this stage, one cannot exclude the activation by certain oncogenes such as WT1 which are highly expressed in ovarian cancer and known to increase AMHRII expression by one of its isotypes designated “–KTS”." (PMID 33917111, 2021).
ovarian carcinoma (continued). "Herein, we used bioinformatics and other methods to identify important pathways and hub genes in ovarian cancer affected by WT1." (PMID 34692659, 2021). "For example, in ovarian cancer, MET of cancer‐associated MSCs mediated by Wilms’ tumor 1 (WT1) and EZH2 promote metastatic tumors growth in distant organs." (PMID 34977870, 2021). "Previous studies have shown that the WT1 gene is highly expressed in epithelial ovarian cancer tissues, and can regulate the metastasis and invasion of ovarian cancer through the E-cadherin and ERK1/2 signaling pathways." (PMID 34692659, 2021). "Our findings provide evidence outlining mechanisms involving WT1 gene expression in ovarian cancer and provides a rational for novel treatment of ovarian cancer." (PMID 34692659, 2021). "Wilms tumor 1 (WT-1) is an intracellular protein that overexpressed in many solid tumors including ovarian cancer, therefore it is targeted by specific cytotoxic T lymphocytes when presented by MHC molecules." (PMID 33584699, 2020). "Results show ERα occupancy in HOXB3, TGM1, TWIST2, and WT1 gene promoters, which are all relevant for ovarian cancer, and DOT1L co-binding with ERα only in the TWIST2 and WT1 promoter regions." (PMID 31689915, 2019). "We found that, similar to SHMT1 knockdown, WT1 knockdown also prevented the ability of ovarian cancer cells to form colonies in soft agar." (PMID 28288142, 2017). "The tumors produced with ovarian cancer sera-exposed cells, were weakly positive for WT-1 and EMA suggesting a tendency to differentiate toward ovarian carcinoma." (PMID 28854931, 2017). "We found that expression of exogenous SHMT1 in WT1 shRNA-expressing ovarian cancer cells rescued the cells' ability to form colonies in soft agar." (PMID 28288142, 2017). "WT1, PAX8, and GCDFP-15 play a major role in distinguishing between primary and metastatic breast cancers from ovarian cancer, and over 90% of ovarian serous carcinomas are WT1 positive." (PMID 27047697, 2016). "For ovarian cancer, the prognostic value of WT1 was evaluated only in univariate model (metaHR = 1.31, 95%CI = 0.81–2.10), because only 1 study reported multivariate HR." (PMID 25748047, 2015). "For ovarian cancer, the prognostic value of WT1 was demonstrated only in univariate model (metaHR = 2.49, 95%CI = 1.79–3.44)." (PMID 25748047, 2015). "Our findings that overexpression of WT1 in LNCaP cells increased their migration potential, is in agreement with those reported in an ovarian cancer cell line where the constitutive expression of the WT1 A isoform promoted cell migration and invasion." (PMID 23298185, 2013). "A recent study showed that WT1 is rather dedicated to distinguish between serous and endometrioids ovarian carcinomas." (PMID 20492709, 2010). "Finally, immunohistochemistry also showed a strong membrane immunoreactivity for Wilms’ Tumor One (WT1), a typical marker of ovarian cancer." (PMID 40963863, 2025).
ovarian carcinoma (continued). "A phase I clinical study showed that the combination of galinpepimut-S with nivolumab showed a tolerable toxicity profile and induced immune phenotypic changes and WT1-specific IgG production in patients with WT1-expressing ovarian cancer, with a 1-year PFS of 70%." (PMID 39861694, 2025). "Further identification of a novel P-tWT1 isoform in AML and ovarian cancer adds to a long list of previously identified human WT1 isoforms, but only the second of its kind that stem from an intragenic TSS, as most isoforms arise from alternative splicing combinations." (PMID 38977895, 2024). "Finally, we determined the prognostic values of WT1 and tWT1 for ovarian cancer patients using TCGA-OV." (PMID 38977895, 2024). "Our study not only demonstrates the importance of culture conditions that better mimic those observed in primary cancers, especially with regards to hypoxia, but also identifies a novel isoform of WT1 which correlates with poor long-term survival in ovarian cancer." (PMID 38977895, 2024). "WT1 usually express in ovarian cancer especially in High-grade serous carcinoma." (PMID 36670456, 2023). "WT1 protein expression in ovarian cancer tissues was significantly higher than that in normal tissues, and was found to be positively correlated with clinical stage, age, and grades of ovarian cancer." (PMID 34692659, 2021). "WT1 is also used as a marker for the diagnosis and prognosis of ovarian cancer." (PMID 34692659, 2021). "However, the signaling pathways, functional pathways, and key genes involved in WT1 regulation of ovarian cancer need to be further defined." (PMID 34692659, 2021). "We analyzed the expression of these genes using the GEPIA website tools, and analyzed the relationship between these genes and the prognosis of ovarian cancer using the Kaplan-Meier plotter online tool, and finally analyzed the interaction between the selected genes and WT1." (PMID 34692659, 2021). "Wilms tumor gene (WT1) is used as a marker for the diagnosis and prognosis of ovarian cancer." (PMID 34692659, 2021). "In addition, a downregulation of PARW (PRKC apoptosis WT1 regulator), whose reduction in tissues was recently described to have a prognostic value for ovarian cancer progression was detected." (PMID 35251951, 2021). "Although there were differences with the results of previous studies, these data also indicate that WT1 may play an important role in the pathogenesis of ovarian cancer." (PMID 34692659, 2021). "We used transcriptome sequencing technology to analyze the effects of WT1 on the DEGs in the ovarian cancer cell line SKOV3, and analyzed the signaling pathways, molecular functions, and the associated biological processes, and constructed a PPI network of DEGs and performed module analysis." (PMID 34692659, 2021). "We found that WT1 knockdown in ovarian cancer cell lines resulted in reduced SHMT1 expression." (PMID 28288142, 2017). "Subgroup analyses by cancer type showed that WT1 positive expression had an unfavorable impact on OS for patients with ovarian cancer (metaHR = 1.57, 95%CI = 1.10–2.24), endometrial cancer (metaHR = 1.96, 95%CI = 1.04–3.72) and non-carcinoma malignancies (metaHR = 1.59, 95%CI = 1.07–2.37)." (PMID 25748047, 2015). "When attempting to differentiate between primary gastric cancer and metastasis from ovarian cancer, it should be noted that a monoclonal antibody panel for WT1, CK7 and CK20 may facilitate this discrimination." (PMID 25663876, 2015). "Since ovarian cancer was the most common cancer type reported in the current meta-analysis, we conducted overall and subgroup (uni/multivariate) analyses to explore the correlations of WT1 expression with prognosis in these patients." (PMID 25748047, 2015).
ovarian carcinoma (continued). "In fact, two large scale studies with a sample size ≥50011, 24 also found that WT1 might be of limited prognostic value in ovarian cancer patients under multivariable model." (PMID 25748047, 2015). "WT1 is expressed at a high frequency in patients with epithelial ovarian cancer, and it is significant in determining whether a serous carcinoma is primary or metastatic." (PMID 25663876, 2015). "Furthermore, it has been reported previously that PAX8 is expressed in serous, endometrioid, and mucinous ovarian cancer while expression of WT1 is restricted to the serous subtype of ovarian cancer." (PMID 24603706, 2014). "WT1 was dominantly stained in nuclei of ovarian cancer cells." (PMID 24715586, 2014). "WT1 may be a novel therapeutic target for improving the prognosis of ovarian cancer." (PMID 38028542, 2023). "However, the molecular mechanisms involving WT1 in ovarian cancer require further study." (PMID 34692659, 2021). "Therefore, IGFBP1, FBN1, SERPINA1 not only have complex interactions with WT1, but also may jointly regulate the migration and invasion of ovarian cancer cells." (PMID 34692659, 2021). "Furthermore, published evidence has shown that antigen-specific spontaneous immune response are beneficial for different solid malignancies—MSLN in pancreatic cancer, CA125 in ovarian cancer, and WT1 in mesothelioma —and has driven us to explore the expression of these antigens on MPM." (PMID 29100432, 2017). "Therefore, studies attempting to clarify the specific association between WT1 expression and prognosis in subtypes of ovarian cancer are strongly encouraged, as they offer the distinct possibility of advancing our insights into the clinical implications of WT1 expression in ovarian cancer." (PMID 25748047, 2015). "Recently, the detection model of CTCs based on the expression of EpCAM, MUC1, and Wilms tumor protein WT1 showed significantly higher specificity than CA125 (92% vs. 82%), especially in early-stage ovarian cancer (74% vs. 58%)." (PMID 38275400, 2024). "The two markers, WT-1 and PAX8, are commonly used to differentiate ovarian cancer from other tumors of epithelial origin." (PMID 37337182, 2023). "In an in vitro assay, WT1 CAR-T cells identified and lyzed WT1+/HLA-A*02:01+ tumor cell lines (AML, AML-14; CML, BV173; ovarian cancer, OVCAR3)." (PMID 36261831, 2022). "The results of RT-qPCR and western blotting showed that compared with the other three ovarian cancer cell lines Coav-3, OVCAR3, and A2780, the expression of WT1 in SKOV3 was significantly higher." (PMID 34692659, 2021). "The expression of WT1 in ovarian cancer of different grades and ages was higher than that of normal tissues, and WT1 showed a significant correlation with OS and PFS of ovarian cancer." (PMID 34692659, 2021). "In order to explore the potential significance of WT1 in ovarian cancer, we used the online website UALCAN to analyze the pan-cancer expression of WT1 and its expression in ovarian cancer of different grades, stages, and ages." (PMID 34692659, 2021). "The results showed that WT1 is highly expressed in ovarian cancer and is closely related to the overall survival and progression-free survival (PFS) of ovarian cancer." (PMID 34692659, 2021). "In ovarian cancer cell line SKOV3, WT1 downregulation increased the mRNA expression of 638 genes and decreased the mRNA expression of 512 genes, which were enriched in the FoxO, AMPK, and the Hippo signaling pathways." (PMID 34692659, 2021).